PKD1 (polycystin 1, transient receptor potential channel interacting)
Diseases named in the same sentence as PKD1 in open-access papers (continued):
Sharing a sentence is not in itself a finding about the gene and the disease.
breast cancer (continued). "We utilised two breast cancer model cell lines, MCF-7 and MDA-MB-231, to investigate the role of PKD1 in cell invasion." (PMID 19243594, 2009). "Although it is not clear whether the increased mRNA level translates into an enhanced protein level, this supports the idea that PKD1 is a potential tumor suppressor, whereas PKD3 has oncogenic functions in breast cancer." (PMID 37293129, 2023). "We conducted an analysis of PKD mRNA expression levels in breast cancer using the TCGA database that revealed a decrease in PKD1 expression and an increase in PKD3 expression, whereas PKD2 levels are unchanged in basal-like breast cancer compared with normal tissue." (PMID 37293129, 2023). "We have identified the serine/threonine kinase PKD1 as a new non-genomic functional target of BPA in breast cancer cells in vitro." (PMID 32082170, 2019). "Here, the analysis of four breast cancer cell lines expressing PKD1, or not, and/or ERα revealed that only both the PKD1- and ERα-positive MCF-7 cells responded to BPA." (PMID 32082170, 2019). "BPA-stimulated PKD1 phosphorylation is one of the strongest arguments for designating PKD1 as a non-genomic target of BPA and is illustrated in two PKD1-expressing breast cancer cell models." (PMID 32082170, 2019). "In the current study, we found that PKD2 and PKD3 but not PKD1 were preferentially overexpressed in breast cancer and involved in regulating cell proliferation and metastasis." (PMID 30652415, 2019). "Consequently, in breast cancer, the transition from a less aggressive to a metastatic phenotype is characterized by PRKD1 (PKD1) gene promoter methylation and downregulation of PKD1 expression." (PMID 30555634, 2018). "To date, there are no reports linking PKD2 to focal adhesion (FA) function, except one study indirectly showing that PKD (as detected with a pan-antibody that picks up PKD1 and PKD2), as well as cortactin and FA-localized paxillin can be isolated from invadopodia of breast cancer cells." (PMID 28842658, 2017). "Highly invasive breast cancer cell lines such as MDA-MB-231 and BT-20 do not express PKD1, while minimally invasive breast cancer cell lines such as MCF-7 and normal mammary epithelial cells such as MCF-10A show different levels of PKD1 expression." (PMID 26848698, 2016). "The differential expression pattern of PKD2 and PKD3 when compared to PKD1 in breast cancer suggests that the PKD family members do not exhibit the same functions in biological processes like EMT and cell migration." (PMID 26848698, 2016). "Although PKD1 has been shown to be downregulated in many cancers, including prostate and breast cancers, its expression patterns and role in colon cancer has never been investigated." (PMID 25149539, 2014). "Because of its negative regulation of cell motility, it is not surprising that downregulation of PKD1 has been described for advanced gastric, prostate and breast cancers." (PMID 23971832, 2013). "We now show that breast cancer cell lines can be divided into cells that express PKD1 and cells that do not express PKD1." (PMID 23971832, 2013). "PKD1 expression was absent in highly invasive breast cancer cell lines including MDA-MB-231, T47D and SKBR3." (PMID 19243594, 2009). "We found that PKD1 expression at the mRNA level is absent in the highly invasive breast cancer cell lines SKBR3, T47D and MDA-MB-231." (PMID 19243594, 2009). "Similarly, PKD2 and PKD3, but not PKD1, were expressed in the highly metastatic breast cancer cell lines MDA-MB-231 and MDA-MB-468." (PMID 33807058, 2021). "To further assess the role of PKD1 in human breast cancer, we evaluated by qRT-PCR, as described in ‘Materials and methods’, the expression of PRKD1 gene (encoding PKD1) in 7 non-cancerous breast epithelial cell lines and 31 breast cancer cell lines." (PMID 25287328, 2014).
breast cancer (continued). "Since this cell line is ERα-negative, the results from their study and our present study suggest that PKD1 may have different roles in the regulation of breast cancer invasion depending on the expression or not of ERα." (PMID 25287328, 2014). "In breast cancer cells PKD1 is a negative-regulator of cell migration and invasion." (PMID 22276203, 2012). "Additionally, PKD1 is not expressed in highly invasive breast cancer cell lines, whereas non-invasive or very low-invasive breast cancer cell lines express PKD1." (PMID 19243594, 2009). "Even though it is not known whether this mechanism also occurs in breast cancer cells, both observations together could indicate that PKD1 silencing and PKD3 overexpression, through different mechanisms, mutually converge in the activation of the mTORC1-S6K axis." (PMID 37293129, 2023). "Strikingly, SNAI1 protein expression levels correlated with lymph node invasion while a negative correlation of active PKD1 and FBXO11 with SNAI1 was observed in clinical breast cancer samples." (PMID 37293129, 2023). "In contrast, PKD1 expression is absent and PKD2 and PKD3 expression levels are elevated in breast cancer." (PMID 34249722, 2021). "Unlike PKD1 and PKD3, the expression pattern of PKD2 remains relatively unchanged during breast cancer progression." (PMID 26848698, 2016). "In this context, the higher PKD3 levels during breast cancer progression compared with PKD2 and the near absence of PKD1 expression suggest that PKD3 activity may be independent of the expression of the other isoforms, which would support the idea of an autonomously functioning oncogene." (PMID 37293129, 2023).
prostate carcinoma (25 papers, 2009 to 2023). A carcinoma that arises from epithelial cells of the prostate gland. "More interestingly, phosphorylation of E-cadherin by PKD1 was associated with increased cellular aggregation and decreased cellular motility in prostate cancer." (PMID 33807058, 2021). "Reduced PKD1 expression was associated with increased tumor invasiveness and its overexpression in prostate cancer cells was shown to inhibit tumor cell proliferation." (PMID 30419840, 2018). "The protein kinase D (PKD) family, particularly PKD1, has been implicated in prostate cancer biology." (PMID 28077787, 2017). "Previous work from our group has implicated an important role for PKD1 in prostate cancer including modulation of E-cadherin, β-catenin functions, and androgen receptor signaling pathways." (PMID 25149539, 2014). "Previous work from our laboratory has revealed the association of PKD1 downregulation with the progression of prostate cancer." (PMID 22523587, 2012). "PKD1 is necessary for normal physiology of the prostate cells and its down regulation is associated with the progression of prostate cancer." (PMID 22523587, 2012). "The decreased expression of PKD1 has been associated with the progression of prostate cancer." (PMID 22523587, 2012). "Previous work from our laboratory has implicated a critical role for PKD1 in prostate cancer." (PMID 22523587, 2012). "Moreover, in human prostate cancer progressing to androgen independence, the loss of PKD1 is seen." (PMID 26848698, 2016). "In line with this, analysis of two DNA microarray datasets with prostate cancer patients correlated PKD1 expression with higher E-cadherin expression levels and lower metastasis rates." (PMID 37293129, 2023). "For example, direct interaction and phosphorylation of E-cadherin by PKD1 in adherent junctional sites resulted in increased cell aggregation and decreased cell motility in non-invasive LNCaP prostate cancer cells." (PMID 37293129, 2023). "In prostate cancer, PKD1 binds to and phosphorylates the transcription factor Snail on Ser11, thus creating a binding site for 14-3-3 proteins, which interact with Snail and promote its nuclear export." (PMID 35805075, 2022). "In a study, CUR was found to have the capacity to cause protein kinase D1 (PKD1) activation, which can lead to the weakening of the oncogenic signaling via MAPK and β-catenin and subsequent suppression of prostate cancer development." (PMID 33800000, 2021). "We have previously found that PKD1 and PKD3 are upregulated in prostate cancers, but another data also showed that PKD1 was downregulated in metastatic prostate cancer." (PMID 30841931, 2019). "In prostate cancer, PKD1 was downregulated in androgen-independent prostate cancer and increased PKD1 expression blocks cell proliferation and motility." (PMID 30419840, 2018). "In summary, our data implied that androgen suppressed PKD1 expression through an indirect FGFR/FRS2/MEK/ERK pathway in prostate cancer cells." (PMID 28077787, 2017). "In this study, we present the novel findings demonstrating that PKD1 was repressed by androgen/AR at the mRNA and protein levels in androgen-sensitive prostate cancer cells, identifying PKD1 as a novel androgen-repressed gene." (PMID 28077787, 2017). "The cross-regulation of PKD1 by androgen/AR places PKD1 in the AR-induced signaling network, which is critical to prostate cancer progression." (PMID 28077787, 2017). "Our data showed that the transcription of PKD1 was repressed by androgen in androgen-sensitive prostate cancer cells." (PMID 28077787, 2017). "In this study, we report for the first time that PKD1 was tightly regulated by androgen at the transcriptional level in prostate cancer cells and was a novel androgen-repressed gene." (PMID 28077787, 2017). "This evidence supports the notion that PKD1 is repressed by an AR-induced FGFR/FRS2/MEK/ERK pathway in androgen-sensitive prostate cancer cells." (PMID 28077787, 2017).
prostate carcinoma (continued). "R1881 also suppressed PKD1 expression in VCaP cells, a castration-resistant prostate cancer cell line that expresses wild-type AR, in a concentration-dependent manner." (PMID 28077787, 2017). "This notion is further supported by our previous findings that PKD1 protects androgen-sensitive LNCaP prostate cancer cells from phorbol ester-induced apoptosis." (PMID 28077787, 2017). "Reduced expression of PKD1 has been reported in the androgen-independent prostate cancer cell line C4-2 when compared to its parental androgen-dependent LNCaP cells." (PMID 26848698, 2016). "Important roles of PKD1 in regulating E-cadherin and β-catenin mediated adherens junctions have previously been shown in prostate cancer cells." (PMID 25149539, 2014). "Our previous studies demonstrated that dysregulation of PKD1 influences E-cadherin shedding in prostate cancer cells." (PMID 24073251, 2013). "Next, we compared expressions of endogenous Wnt target genes in prostate cancer C4-2 cell line and C4-2 cells that overexpress PKD1 (C4-2/PKD1)." (PMID 22511927, 2012). "CID1893668, CID2011756, and CID5389142 also inhibited phorbol ester-induced endogenous PKD1 activation in LNCaP prostate cancer cells in a concentration-dependent manner." (PMID 23028574, 2012). "Overexpression of PKD1 in prostate cancer C4-2 cell line, which has low endogenous PKD1 expression, suppresses epithelial to mesenchymal transition and tumor incidence in mice xenograft model." (PMID 22511927, 2012). "Herein, we for the first time demonstrated that curcumin attenuates β-catenin/TCF transcription activity via activation of PKD1 in prostate cancer cells." (PMID 22523587, 2012). "PKD1 has also been shown to increase the levels of membrane β-catenin and cell-cell interaction in prostate cancer cells." (PMID 22523587, 2012). "This change in β-catenin subcellular localization was also reflected in xenograft mouse studies, implicating the role of curcumin mediated activation of PKD1 in prostate cancer." (PMID 22523587, 2012). "For example, CID755673 and kb-NB142-70 inhibited PKD1 in vitro in the low nanomolar range and suppressed PKD1 autophosphorylation at Ser916 in LNCaP prostate cancer cells in the low micromolar range." (PMID 23028574, 2012). "Our previous work has also illuminated the role of PKD1 in E-cadherin phosphorylation, modulation of cell motility and cell-cell aggregation in prostate cancer cells." (PMID 22523587, 2012). "Overall, our findings herein have revealed a novel molecular mechanism of curcumin action via the activation of PKD1 in prostate cancer cells." (PMID 22523587, 2012). "The analogs also demonstrated increased inhibition of PMA-induced autophosphorylation of endogenous PKD1 in LNCaP prostate cancer cells when compared to the parental compound." (PMID 20444281, 2010). "This compound, previously identified as a novel PKD inhibitor, inhibited PKD1 with an IC50 of 182 nM in vitro, and blocked cancer-associated properties of prostate cancer cells." (PMID 20444281, 2010). "Our results on PKD1 in invasive breast cancer are in consensus with data obtained for gastric cancer and prostate cancer, where decreased expression of PKD1 was described in most of the cases analysed." (PMID 19243594, 2009). "Therefore, PKD1 down-regulation in prostate cancer further activates the Wnt/β-catenin signaling pathway by destabilizing the E-cadherin/β-catenin complex, which leads to increased amounts of β-catenin available for translocation to the nucleus." (PMID 35805075, 2022). "Therefore, PKD1-induced E-cadherin shedding suppresses prostate cancer cell proliferation as well as colony formation." (PMID 35805075, 2022). "On the contrary, PKD1 inhibits prostate cancer cell proliferation." (PMID 35805075, 2022).
prostate carcinoma (continued). "The authors further demonstrated a reverse correlation between PKD1 and MTA1 expression in a transgenic adenocarcinoma of the mouse prostate (TRAMP) model and in samples of human prostate cancer, in which PKD1 expression decreased, whereas MTA1 expression increased with progressed tumor stage." (PMID 33807058, 2021). "Furthermore, there was a significant PKD1 downregulation after progression from androgen-dependent to androgen-independent prostate cancer, which influencedthe motility and invasion of prostate cancer through interaction with E-cadherin." (PMID 33800000, 2021). "Interestingly, in other cancer types including breast, gastric and prostate cancer, PKD1 was found to be downregulated in primary tumors or metastases." (PMID 30419840, 2018). "PKD1 may be targeted to enhance the therapeutic response to anti-androgens in prostate cancer treatment." (PMID 28077787, 2017). "The upregulation of prosurvival PKD1 by anti-androgens may contribute to therapeutic resistance in prostate cancer treatment." (PMID 28077787, 2017). "Here, we examined the cross-regulation of PKD1 by androgen signaling in prostate cancer cells." (PMID 28077787, 2017). "Our findings suggested that the prosurvival function of PKD1 may have significant implications in prostate cancer progression and therapy resistance." (PMID 28077787, 2017). "Thus, SD-208 is structurally distinct pan-PKD inhibitor that elicits targeted inhibition of PKD1 kinase activity in prostate cancer cells." (PMID 25747583, 2015). "Downregulation of PKD1 has been documented in breast and prostate cancers." (PMID 25149539, 2014). "A similar function of PKD1 was demonstrated in prostate cancer cells." (PMID 25149539, 2014). "It was reported that CUR could activate protein kinase D1 (PKD1) suggesting that suppressing of β-catenin transcriptional activity prevents growth of prostate cancer." (PMID 23970932, 2013). "In human normal prostate tissue, the phosphorylated T120 β-catenin is mainly localized to the trans-Golgi network (TGN, 22/30, 73%), and this pattern is significantly altered in prostate cancer (14/197, 7.1%), which is consistent with known down regulation of PKD1 in prostate cancer." (PMID 22511927, 2012). "The activation of PKD1 and the reduction of β-catenin transcriptional activity by curcumin may also impact androgen receptor (AR) signaling in prostate cancer, since both PKD1 and β-catenin modulate AR function." (PMID 22523587, 2012). "Thus, since active PKD1 is involved in shuttling of nuclear β-catenin out of the nucleus, our study suggests a novel mechanistic role for curcumin mediated attenuation of β-catenin/TCF activity and prostate cancer growth through activation of PKD1." (PMID 22523587, 2012). "Herein, we have demonstrated that curcumin activates PKD1, resulting in changes in β-catenin signaling by inhibiting nuclear β-catenin transcription activity and enhancing the levels of membrane β-catenin in prostate cancer cells." (PMID 22523587, 2012). "The nutraceutical compound curcumin may act as a chemo-preventive agent to inhibit or delay the onset of prostate cancer via the activation of PKD1." (PMID 22523587, 2012). "Our work has revealed the ability of PKD1 to inhibit the functions of β-catenin in prostate cancer." (PMID 22523587, 2012). "Interestingly, curcumin treatment alters the subcellular localization of PKD1 in prostate cancer cells." (PMID 22523587, 2012). "The natural macrolactone Bryostatin 1 activates PKD1 in prostate cancer cells." (PMID 22523587, 2012). "To determine whether the compounds are active in cells, we tested their ability to inhibit activation of PKD1 by phorbol 12-myristate 13-acetate (PMA) in LNCaP prostate cancer cells." (PMID 20444281, 2010).